BASP1 (brain abundant membrane attached signal protein 1)
Synonyms: NAP22; NAP-22; CAP23; CAP-23
Tractability: Antibody: its Gene Ontology location is reachable by antibodies, with high confidence; UniProt places it where antibodies can reach, with medium confidence; the Human Protein Atlas places it where antibodies can reach. PROTAC: UniProt records ubiquitination sites on it; ubiquitination databases record sites on it; its protein half-life has been measured.
Gene: Protein-coding gene on chromosome 5 (17,065,598 to 17,276,843, forward strand). Ensembl gene ENSG00000176788.
Subcellular location: Cell membrane; Cell projection, growth cone
Subcellular location (Human Protein Atlas): Plasma membrane
Pathways (Reactome):
Signal Transduction: RHOF GTPase cycle
Gene Ontology:
Molecular function: calmodulin binding; protein binding; protein domain specific binding; transcription corepressor activity; transcription cis-regulatory region binding
Biological process: negative regulation of DNA-templated transcription; protein homooligomerization; substantia nigra development; supramolecular fiber organization; diaphragm development; gonad development; mesenchymal to epithelial transition; metanephric mesenchyme development; podocyte differentiation; positive regulation of heart growth; positive regulation of metanephric ureteric bud development; thorax and anterior abdomen determination
Cellular component: COP9 signalosome; cytoplasm; extracellular exosome; nuclear matrix; nucleus; plasma membrane; PML body; vesicle; cytoskeleton; nuclear speck; chromatin; growth cone
Genetic constraint (gnomAD): Loss-of-function variants: 2 observed, 4.68 expected, observed/expected ratio (o/e) 0.43, 90% interval 0.17 to 1.32. That is too few expected variants to judge how well the gene tolerates losing a copy. Missense variants: 352 observed, 296.86 expected, observed/expected ratio (o/e) 1.19, 90% interval 1.09 to 1.29. Synonymous variants: 187 observed, 149.49 expected, observed/expected ratio (o/e) 1.25, 90% interval 1.11 to 1.41.
Homologues: Orthologues: macaque BASP1 (99% identical), chimpanzee BASP1 (93% identical), rabbit BASP1 (81% identical), mouse Basp1 (72% identical), rat Basp1 (70% identical), guinea pig BASP1 (70% identical), dog BASP1 (66% identical), tropical clawed frog basp1 (59% identical).
Diseases named in the same sentence as BASP1 in open-access papers:
BASP1 is named in the same sentence as 65 diseases in open-access papers, as found by Europe PMC text mining. Sharing a sentence is not in itself a finding about the gene and the disease. The quoted sentences say what the papers report.
acute myeloid leukemia (7 papers, 2019 to 2021). Acute myeloid leukemia (AML) is a group of neoplasms arising from precursor cells committed to the myeloid cell-line differentiation. "Methylation-associated silencing of BASP1 contributes to leukemogenesis in acute myeloid leukemia (AML)." (PMID 31058089, 2019). "In contrast, nuclear BASP1 inhibits Myc-induced fibroblast transformation 9, suppresses the proliferation of acute myeloid leukemia 10, and acts as a transcriptional corepressor in breast cancer 11, suggesting that BASP1 harbors tumor inhibitory functions." (PMID 33042262, 2020). "For instance, BASP1 is confirmed to repress the growth of acute myeloid leukemia by inhibiting cell proliferation and promoting cell apoptosis." (PMID 33426068, 2020). "Besides, BASP1 plays a tumor suppressive role in vitro and was targeted as a treatment in acute myeloid leukemia by promoter methylation." (PMID 34041244, 2021).
breast carcinoma (7 papers, 2017 to 2023). "In all, 40% of the genes that are regulated by tamoxifen in breast cancer cells are BASP1 dependent, including several genes that are associated with tamoxifen resistance." (PMID 28492543, 2017). "Moreover, BASP1 is expressed in breast cancer tissue and is associated with increased patient survival." (PMID 28492543, 2017). "Moreover, BASP1 is expressed in breast cancer tissue and is associated with enhanced survival." (PMID 28492543, 2017). "In breast cancer, BASP1 enhances the efficacy of tamoxifen by synergizing with the estrogen receptor alpha, and a better prognosis for survival is associated with increased BASP1 expression." (PMID 37243901, 2023). "Both TMX and TFP induce apoptosis in cholangiocarcinoma, and it is interesting that the CaM interactor BASP1 was reported to enhance the antitumorigenic effect of TMX in breast cancer." (PMID 31944520, 2020). "BASP1 elicits tumor suppressor activity in breast cancer and BASP1 expression levels correlate with increased patient survival." (PMID 31058089, 2019). "BASP1 elicits tumour-suppressor activity in breast cancer cells and enhances the antitumourigenic effects of tamoxifen treatment." (PMID 28492543, 2017). "This is consistent with the enhanced survival of breast cancer patients with higher levels of tumour BASP1." (PMID 28492543, 2017). "Analysis of another ER-positive breast cancer cell line (T47D) confirmed that BASP1 immunoprecipitates contained more ERα after treatment of the cells with tamoxifen." (PMID 28492543, 2017). "Taken together, these results suggest that expression of BASP1 in breast cancer tissue is related to ERα expression and that BASP1 likely acts as a tumour suppressor in breast cancer." (PMID 28492543, 2017). "Here we report that the transcriptional corepressor BASP1 interacts with ERα and in breast cancer cells, this interaction is enhanced by tamoxifen." (PMID 28492543, 2017). "We next analysed a breast cancer tissue array to determine BASP1 and ERα expression by immunohistochemistry (IHC)." (PMID 28492543, 2017). "We find that BASP1 acts as a major selectivity factor in the transcriptional response of breast cancer cells to tamoxifen." (PMID 28492543, 2017). "In breast cancer, BASP1 could enhance the anticancer effects of tamoxifen treatment, and patients with high BASP1 were associated with better prognosis." (PMID 36776328, 2023). "In this context, it is interesting to observe that the BASP1-interaction partner CaM induces ERα dimerization, and that disruption of the ERα/CaM interaction could represent a potential therapeutic strategy for targeting ERα-positive breast cancers." (PMID 31058089, 2019). "Oncomine database analysis revealed that BASP1 mRNA was increased in most types of cancers, including HNSCC, breast cancer, kidney cancer, pancreatic cancer, and lung cancer." (PMID 33247706, 2020). "Overexpression of WT1 induces a significant increase in the abundance of endogenous MYC protein in breast cancer cells, whereas a WT1/BASP1 complex represses the MYC promoter." (PMID 31058089, 2019). "However, few studies have reported the BASP1 is downregulated in some cancer, but we found that BASP1 is up-regulated in many cancers including HNSCC, breast cancer, esophageal cancer, kidney cancer, lung cancer, lymphoma, pancreatic cancer, and sarcoma." (PMID 33247706, 2020). "Our histological analysis found that BASP1 is not expressed in normal breast tissue but is frequently present at all stages of breast cancer, but particularly in the benign tumours." (PMID 28492543, 2017).
cervical cancer (7 papers, 2017 to 2023). A primary or metastatic malignant neoplasm involving the cervix. "We determined the functional role of BASP1 in cervical cancer development by gain or loss of BASP1 in ME-180 and HT-3 cells." (PMID 29089860, 2017). "Besides, BASP1 upregulation was considered as a high-risk factor in lung adenocarcinoma, cervical cancer, as well as in HNSCC." (PMID 36776328, 2023). "Elevated levels of the tumor suppressor BASP1 is known to promote tumor growth and correlate with clinical aggressiveness in cervical cancer." (PMID 37839701, 2023). "Recent studies have also reported that BASP1 expression is upregulated in several cancers, including lung cancer, cervical cancer, head and neck squamous cell carcinoma, and tongue squamous cell carcinoma, and is associated with poor prognosis." (PMID 37243901, 2023). "In cervical cancer, BASP1 promotes the proliferation and colony‐forming ability of tumor cells and accelerates the progression of the cell cycle." (PMID 37243901, 2023). "More recent study demonstrated that BASP1 highly expressed in cervical cancer that promoted cancer growth." (PMID 33247706, 2020). "Accordingly, BASP1 is downregulated in most human tumors and tumor cell lines, except of distinct cervical cancer cells where BASP1 levels are paradoxically high." (PMID 31058089, 2019). "Gene set enrichment analyses (GSEA) demonstrated that BASP1 expression correlated significantly with progression and development of cervical cancer, revealing that BASP1 is an oncogene in cervical cancer." (PMID 29089860, 2017). "BASP1 was upregulated in the cervical cancer cell lines, which was consistent with our previous results for BASP1 abundance in cervical cancer tissues." (PMID 29089860, 2017). "BASP1 levels were determined in cervical cancer cell lines and in two papillomavirus-immortalized normal cervical cell lines." (PMID 29089860, 2017). "We confirmed these results by downregulating BASP1 in the indicated cervical cancer cell lines using siRNAs." (PMID 29089860, 2017). "BASP1 also regulates the proliferation and tumorigenicity of cervical cancer; overexpression of BASP1 promoted cellular proliferation and tumorigenicity and knockdown of BASP1 had the opposite effect." (PMID 29089860, 2017). "We demonstrated that BASP1 is an independent prognostic factor for patients with cervical cancer that promotes cervical cancer growth." (PMID 29089860, 2017). "Six paired cervical cancer tissues and matched adjacent normal cervical tissues were used to examine BASP1 protein levels." (PMID 29089860, 2017). "BASP1 was upregulated in cervical cancer, and is a novel unfavorable prognostic factor for patients with cervical cancer." (PMID 29089860, 2017). "Brain abundant membrane attached signal protein 1 was upregulated in cervical cancer tissues and cells, and BASP1 expression levels were higher in patients that had died during follow-up compared with those that survived." (PMID 29089860, 2017). "Western blotting showed that BASP1 levels were higher in cervical cancer tissues than in matched adjacent normal cervical tissues." (PMID 29089860, 2017). "The results showed that BASP1 not only is a novel prognostic factor for patients with cervical cancer, but also promotes the proliferation and tumorigenicity of cervical cancer." (PMID 29089860, 2017). "The MTT assay, colony formation assay, cell cycle assay, anchorage-independent growth assay, and a tumor xenograft model were used to determine the role of BASP1 in the proliferation and tumorigenicity of cervical cancer." (PMID 29089860, 2017). "BASP1 knockdown inhibited the proliferation of cervical cancer and its colony formation ability, suppressed cell cycle progression, and decreased tumorgenicity." (PMID 29089860, 2017). "In this study, we analyzed the relationship between BASP1 expression and clinicopathological parameters in patients with cervical cancer, and studied the role of BASP1 in the cervical cancer growth." (PMID 29089860, 2017).
cervical cancer (continued). "Statistical analysis of BASP1 levels in 136 paraffin-embedded cervical cancer tissues suggested a positive correlation between BASP1 levels and clinical stage, T classification, N classification and survival or mortality." (PMID 29089860, 2017). "We also determined the role of BASP1 in the proliferation and tumorigenicity of cervical cancer; overexpression of BASP1 promoted proliferation, colony formation, cell cycle progression, and tumorigenicity." (PMID 29089860, 2017). "Overexpression of BASP1 promoted the proliferation of cervical cancer and its colony formation ability, accelerated cell cycle progression, and enhanced tumorgenicity." (PMID 29089860, 2017). "Interestingly, one of the top hits in HeLa cells, derived from a rare cervical adenocarcinoma, is the BASP1, which is downregulated in most tumor cell lines except some cervical cancer lines." (PMID 37839701, 2023). "The aim of this study was to determine whether brain abundant membrane attached signal protein 1 (BASP1) is a valuable prognostic biomarker for cervical cancer and whether BASP1 regulates the progression of cervical cancer." (PMID 29089860, 2017). "Our findings suggested BASP1 levels correlated with the clinical aggressiveness of cervical cancer." (PMID 29089860, 2017). "To investigate whether BASP1 regulates the development and progression of cervical cancer, we explored BASP1 expression in cervical cancer tissues and normal cervical epithelium tissues." (PMID 29089860, 2017). "This suggested that BASP1 promoted the tumorigenicity of cervical cancer." (PMID 29089860, 2017). "Cox regression analysis demonstrated that BASP1 is an independent prognostic factor for patients with cervical cancer, and thus could be used to predict their prognosis." (PMID 29089860, 2017). "The MTT assay indicated that overexpression of BASP1 promoted cervical cancer cell proliferation." (PMID 29089860, 2017). "In the present study, we demonstrated that BASP1 plays an important role in cervical cancer." (PMID 29089860, 2017). "Statistical analyses were used to examine whether BASP1 was a prognostic factor for patients with cervical cancer." (PMID 29089860, 2017). "Immunohistochemical analysis also revealed that BASP1 was upregulated in cervical cancer tissues." (PMID 29089860, 2017). "We found that BASP1 is a new prognostic factor for cervical cancer, and promotes tumor growth." (PMID 29089860, 2017). "Furthermore, in distinct cervical cancer cells BASP1 even promotes tumor growth." (PMID 31058089, 2019). "To determine the relationship between BASP1 levels and clinicopathological parameters, and whether BASP1 could serve as a new independent prognostic factor, we determined BASP1 levels in a cohort of 136 paraffin-embedded archived cervical cancer tissues using immunohistochemistry." (PMID 29089860, 2017). "We found BASP1 levels were high in cervical cancer, suggesting that BASP1 may be an oncogene." (PMID 29089860, 2017). "Thus, BASP1 abundance correlated significantly with the prognosis of cervical cancer." (PMID 29089860, 2017). "However, the mechanism by which BASP1 promotes the proliferation and tumorigenicity of cervical cancer requires further study; for example, a chromatin immunoprecipitation assay could identify the target genes of BASP1 associated with cervical cancer." (PMID 29089860, 2017). "Conversely, BASP1 is upregulated in cervical cancers and promotes tumorigenicity, thereby identifying it as a novel prognostic factor." (PMID 32084215, 2020). "Brain abundant membrane attached signal protein 1 could serve as a new prognostic factor; therefore, we further determined whether BASP1 regulates tumor growth of cervical cancer." (PMID 29089860, 2017). "However, the role of BASP1 in cervical cancer has not been reported." (PMID 29089860, 2017).
hepatocellular carcinoma (7 papers, 2017 to 2023). A malignant tumor that arises from hepatocytes. "For instance, BASP1 hypermethylation and downregulation in hepatocellular carcinoma were considered as a biomarker for early detection." (PMID 36776328, 2023). "Studies have shown that dysregulated expression and methylation level of BASP1 are directly related to the occurrence and prognosis of cancers, such as hepatocellular carcinoma." (PMID 34041244, 2021). "The BASP1 gene was silenced in several tumour types including hepatocellular carcinoma, thyroid cancer and leukaemias." (PMID 33247706, 2020). "BASP1 expression has also been shown to be downregulated in hepatocellular carcinoma via epigenetic regulation." (PMID 28212542, 2017). "For example, downregulation of BASP1 expression via promoter methylation may potentially be used to diagnose hepatocellular carcinoma in its early stages." (PMID 32084215, 2020). "Moribe and colleagues used a gene microarray and pyrosequencing to screen genes that are methylated specifically in hepatocellular carcinoma (HCC), and found that BASP1 is aberrantly methylated in HCC; its expression is low in HCC, and it can function as a useful biomarker for the diagnosis of HCC." (PMID 29089860, 2017).
melanoma (7 papers, 2017 to 2024). A malignant, usually aggressive tumor composed of atypical, neoplastic melanocytes. "We identified one novel melanoma-susceptibility locus, located at 5p15.1 (rs187843643; BASP1—) (P = 3.53 × 10−8; OR = 1.96, logistic regression)." (PMID 28212542, 2017). "A study in 2017 demonstrated that BASP1 might be a susceptibility locus for malignant melanoma due to its decreased expression in melanoma; however, various ncRNA mutations may also lead to susceptibility to melanoma development." (PMID 39659781, 2024). "For example, the prediction effect of BASP1 on the response rate to immunotherapy was performed in melanoma, which need to be further studied in HNSCC patients in the future." (PMID 36776328, 2023). "The TIDE algorithm was performed to predict the response rate to immunotherapy, which demonstrated that patients with high BASP1 had a better prognosis in anti-PD-1 therapy in melanoma." (PMID 36776328, 2023). "The ncRNA is located 177 kb downstream of brain-abundant-membrane-attached signal protein 1 (BASP1), and authors subsequently found reduced BASP1 expression in melanoma compared with benign nevi." (PMID 37629553, 2023). "BASP1 is downregulated in several mammalian tumors including carcinoma, acute and chronic lymphocytic leukemia, and melanoma." (PMID 31944520, 2020). "In multiple carcinoma, melanoma, and leukemia cells, BASP1 transcription is silenced by promoter methylation, a typical DNA modification in the regulatory regions of tumor suppressors in cancer." (PMID 31944520, 2020). "One study demonstrated an association between increased BASP1 expression in stage III and stage IV melanoma tumor cells and improved melanoma survival." (PMID 28212542, 2017). "We find that BASP1 expression is suppressed in melanoma as compared with benign nevi, providing additional evidence for a putative role in melanoma pathogenesis." (PMID 28212542, 2017). "Furthermore, in multiple carcinoma, melanoma, and leukemia, BASP1 transcription is silenced by promoter methylation, a typical DNA modification in the regulatory regions of tumor suppressors in cancer." (PMID 31058089, 2019). "This implicates a potential tumor-suppressive role for BASP1 in melanoma." (PMID 28212542, 2017). "Consistent with a protective role for BASP1 in melanoma, we found that BASP1 expression was suppressed in melanoma (N = 45) as compared with benign nevi (N = 18) by 0.26 fold (P = 0.007, moderated t-statistic) using publicly available expression data (GEO, GDS1375/GSE3189)." (PMID 28212542, 2017). "Further exploration into the role of the BASP1 locus in melanoma pathogenesis is warranted." (PMID 28212542, 2017). "BASP1 is also downregulated in multiple mammalian tumors like carcinoma, acute, and chronic lymphocytic leukemia (ALL, CLL), or melanoma by direct transcriptional repression, microRNA-guided downregulation, or promoter methylation." (PMID 31058089, 2019).